CYP4A26P (cytochrome P450 family 4 subfamily A member 26, pseudogene)
Synonyms: CYP4A-se1[12]
Gene: Unprocessed pseudogene on chromosome 1 (46,967,679 to 46,967,874, reverse strand). Ensembl gene ENSG00000259832.
Diseases named in the same sentence as CYP4A26P in open-access papers:
CYP4A26P is named in the same sentence as 1 disease in open-access papers, as found by Europe PMC text mining. Sharing a sentence is not in itself a finding about the gene and the disease.
CYP4A26P shares sentences with these, for which no sentence is quoted: lung carcinoma (1 paper).